CDK9 (cyclin dependent kinase 9)
Diseases named in the same sentence as CDK9 in open-access papers (continued):
Sharing a sentence is not in itself a finding about the gene and the disease.
cancer (continued). "The activity of CDK9 is significantly up-regulated in a wide variety of cancer entities, to aid in the overexpression of genes responsible for the regulation of functions, which are beneficial to the cancer cells, like proliferation, survival, cell cycle regulation, DNA damage repair and metastasis." (PMID 34062779, 2021). "Therefore, CDK9 inhibition reduces messenger RNA (mRNA) transcription and prevents the expression of target genes (e.g. Myc and Mcl-1), which together regulate proliferation and cancer cells survival." (PMID 33632038, 2021). "Therefore, the hypothesis that CDK9 could be an anti-cancer therapeutic target has been proposed and are under investigation, based on its pivotal role in transcription elongation." (PMID 33467099, 2021). "Therefore, targeting CDK9 with small molecule inhibitors has emerged as a potential cancer therapy." (PMID 33632038, 2021). "Finally, we discuss the perspective and challenge of CDK9 modulation in cancer." (PMID 32903585, 2020). "Importantly, RA, inhibitors of HDACs, BET bromodomain containing proteins, CDK7, CDK9 and small molecules that bind to G4s have been demonstrated to be effective for the treatment of many types of cancers by targeting their dysregulated transcriptional programs." (PMID 33628735, 2020). "Therefore CDK9 inhibition prevents productive transcription and is associated with a global reduction in mRNA, including genes, such as MYC and MCL-1, which regulate proliferation and survival of cancer cells." (PMID 29471852, 2018). "To determine whether targeting the Mnk-eIF4E axis in cancer cells is an additional mechanism to CDK9 inhibition or a consequence of CDK9 pathway alteration, we conducted experiments utilizing shRNA-mediated CDK9 inhibition to compare with the pharmacological effects of CDKI-73." (PMID 25277198, 2014). "Thus, development of CDK2 and CDK9 inhibitors may also be useful for the development of cancer drugs." (PMID 23140174, 2012). "Cyclin-dependent kinase 9 (CDK9) is a key regulator of transcriptional elongation and DNA repair, supporting cancer cell survival by sustaining the expression of oncogenes and anti-apoptotic proteins." (PMID 41594554, 2025). "Reflecting the close association of CDK9 and BRD4 and their interplay in transcriptional regulation, co-targeting CDK9 and BRD4 has been found to elicit synergistic effects in multiple cancer types." (PMID 40163908, 2025). "Significant attention has been paid to the role that transcriptional CDKs play in cancer, including CDK7, CDK8, CDK9, CDK12, and CDK13." (PMID 40361480, 2025). "Cancer cells rely heavily on CDKs like CDK1, CDK2, and CDK9 for uncontrolled proliferation, whereas normal cells maintain cell cycle control with minimal CDK activity, making them less susceptible to Dinaciclib-induced cytotoxicity." (PMID 40076816, 2025). "Of particular interest is CDK9′s role as a regulator of MYC, a well-studied transcription factor that promotes the growth and progression of many cancer types." (PMID 40163908, 2025). "Their selective CDK9 degrader led to greater downregulation of MYC and anti-apoptotic proteins, resulting in enhanced cancer cell death." (PMID 40574056, 2025). "For example, CDK9 is critical for the continuous expression of genes producing short-lived mRNAs or proteins, such as MYC and MCL-1 that promote cancer cell survival." (PMID 38326887, 2024). "Understanding the mechanisms by which CDK9 and CYP3A4 contribute to cancer development and progression is essential for the development of new therapeutic strategies." (PMID 39498375, 2024).
cancer (continued). "In a recent work, triazole-pyridine-carbamate derivatives were synthesized and evaluated as CDK9 inhibitors; among this series, St.42 showed potent activities against HCT116 cancer cell lines with significant activities on the CDK9 enzyme." (PMID 39404419, 2024). "Using this screen, we developed and optimized a potent and selective CDK9 inhibitor, MC180295, and showed its significant anti-proliferative effects in cancer cell lines, with minimal effects on normal cells." (PMID 38172923, 2024). "We and several others have recently shown that short-term inhibition of CDK9 depletes short-lived transcripts and labile proteins such as MCL1 and MYC to promote cancer cell death." (PMID 38371625, 2024). "In summary, our data demonstrate that simultaneous inhibition of CDK9 and the KRAS/MAPK pathway reciprocally strengthen the anticancer effect of each monotherapy in preclinical models of KRAS‐mutant cancers, including those with KRASi resistance." (PMID 39254172, 2024). "The therapeutic efficacy of CDK9 inhibitors therefore has been reported in MYC-driven and MLL1-rearranged cancers." (PMID 38172923, 2024). "Cyclin-dependent kinase 9 (CDK9), a key regulator of transcription and cell cycle progression, has been identified as a promising path for cancer therapy." (PMID 38534727, 2024). "Clinical trials are underway to assess the safety and efficacy of targeting CDK9 with AZD4573 or VIP-152 in hematological malignancies (e.g., NCT04978779 and NCT03263637) and other advanced cancer types." (PMID 38326887, 2024). "This study reveals the CDK9/PP2A/ERK network involved in transcriptional pause release and complement activation in KRAS‐mutant cancers, which limits the efficacy of CDK9i in vivo." (PMID 39254172, 2024). "Despite distinctive pharmacological mechanisms, CPYPP, CsA, and curcumin were shown for the first time to induce cancer cell paraptosis in a ROS- and CDK7/CDK9-dependent manner." (PMID 38858714, 2024). "CDK9 was also found to interact with the chromatin reader KAP1 and the transcription factor SMAD2, in sustaining transcriptional programs involved in cancer maintenance." (PMID 38172923, 2024). "Meanwhile, mounting evidence implicates CDK9, a transcriptional CDK, as a key driver of high-turnover oncogenes, particularly in MYC-dependent cancers." (PMID 36998071, 2023). "Given the increased expression of c-Myc in T-PLL, and the role of CDK9 in Myc-addicted cancers, in conjunction with the Mcl-1 dependence observed in a subset of T-PLL, CDK9 inhibition is an attractive and highly rational approach." (PMID 37569479, 2023). "SNS032 is known as a new and effective selective CDK9 inhibitor (CDK9—cyclin-dependent kinase 9), responsible for TRAIL resistance of cancer cells." (PMID 37242569, 2023). "The depletion of CDK9 by GFH009 provides further evidence that this compound inhibits growth by effectively and efficiently depriving oncogene-addicted cancer cells with high rates of DNA transcription of crucial survival signals." (PMID 38117531, 2023). "CDK9 inhibitors, such as flavopiridol, SNS-032, and roscovitine, have been demonstrated to be efficient in cancer treatment through downregulation of these prosuvival and antiapoptotic proteins." (PMID 35088192, 2023). "In the field of cancer therapy, inhibitors of SE complex proteins, such as BRD4, CDK7, or CDK9, show great potential." (PMID 37501079, 2023). "This analysis focused on the functionally significant components of the multimeric RNAPII complex, including BRD4, HEXIM1, Spt5, NELF-A, Cyclin T, CDK9, LARP-7, and Caspase-8, which collectively serve as a regulatory hub in gene expression in cancer cells." (PMID 38201534, 2023). "Co-targeting of CDK9 and FLT3 is a promising two-pronged strategy to overcome resistance as the former plays a role in the transcription of cancer cell-survival genes." (PMID 35267421, 2022).
cancer (continued). "Although ERBB3 and CDK9 belong to CATH-FunFams with some propensity for side effects, these targets are still of interest and being considered for other cancers." (PMID 35035776, 2022). "CDK9 reactivates epigenetically silenced genes in cancer, and inhibition of CDK9 by drugs such as flavopiridol, dinaciclib, seliciclib, SNS-032, and RGB-286638 is exploited in cancer therapy." (PMID 36248973, 2022). "Surprisingly, inhibition of CDK9 by a small molecule inhibitor, i-CDK9, enhances MYC expression and only simultaneous inhibition of CDK9 and BRD4 can efficiently induce growth arrest and apoptosis in cancer cells." (PMID 35053227, 2022). "As CDK9 has been reported as a regulator of transcription and cancer cell growth, we further examined the proliferation rate of PARP inhibitor-resistant and inhibitor-sensitive cells depleted of CDK9." (PMID 36253486, 2022). "Similarly, CDK9 expression was higher in the low-grade group than in the high-grade group, which can be attributed to the increasing independence from cell cycle regulators in higher-grade cancers and suggest that the role of CDK9 may be marginalized as the disease progresses." (PMID 35326643, 2022). "highlights the potential of OGT inhibitors in combination with other therapies to benefit cancer-specific vulnerabilities and reports a novel synthetic lethal interaction between OGT and CDK9 inhibitors." (PMID 36439421, 2022). "Two potent CDK9 inhibitors, AT7519 and flavopiridol (FVP), have been widely used in clinical trials as anti-cancer therapies." (PMID 34523672, 2022). "Accordingly, BRD4 inhibition impairs CDK9 recruitment to MYC, reduces MYC transcripts levels, down-regulates Myc-dependent target genes, and has anti-proliferative effects in cancer cells." (PMID 34146121, 2021). "Cyclin-dependent kinase 9 (CDK9) is a promising prognostic marker and therapeutic target in cancers." (PMID 33122847, 2021). "Wogonin, a natural plant-based flavone was shown to target CDK9 activity, in an ATP-competitive manner, resulting in lower pS2 and MCL-1 levels and increased apoptosis in CLL and multiple other cancer entities." (PMID 34062779, 2021). "This experiment strongly suggests that combined inhibition of CDK9 and BRD4 would be a useful strategy to combat cancers, which show high levels of MYC or other genes, whose expression is regulated by super-enhancers." (PMID 34359807, 2021). "They had proposed combing the inhibitors of CDK9 with those against BRD4 and cMYC to efficiently inhibit the proliferation and promote apoptosis of cancer cells." (PMID 34062779, 2021). "To determine the potential contribution of inhibiting CDK3 and CDK5, as compared to CDK2 and CDK9, we analyzed data publicly available from genome-wide CRISPR-Cas9 screens in >700 cancer cell lines (from the Cancer Dependency Map project)." (PMID 32645016, 2020). "Taken together the underlying mechanisms for the observed markedly promoted growth inhibition and apoptosis induction by combined therapy can be the concomitant suppression of CDK1, CDK9, c-FIP, Mcl-1 and Bcl-2 and upregulation of Bax in cancer cells." (PMID 32375399, 2020). "Inhibition of both CDK9 and BRD 4 has been reported synergistically to induce growth arrest and apoptosis of cancer cells including MM." (PMID 32559187, 2020). "The results shown are consistent with the principal anti-cancer effects of the drug being mediated by inhibition of CDK2 and CDK9, for which IC50 values are 4.5 and 26 nM respectively." (PMID 32645016, 2020). "MC180295 is also a highly selective CDK9 inhibitor (> 22 fold, IC50 = 5 nM) that has broad anti-cancer activity in vitro and in vivo." (PMID 32559187, 2020). "Cyclin-dependent kinase 9 (CDK9) is a central regulator of eukaryotic transcription and a promising therapeutical target in cancer and other diseases." (PMID 31857848, 2019). "Cyclin‐dependent kinase 9 (CDK9), which plays a crucial role in transcription, has emerged as a target for cancer treatment." (PMID 31398271, 2019).
cancer (continued). "Dysregulation in the CDK9 pathway has been observed in AML and other hematologic malignancies and in solid tumors, making it an attractive target for cancer therapeutics." (PMID 29471852, 2018). "Critically, CDK9-mediated transcription of MCL-1 and MYC plays an important role in growth and survival of cancer cells, and dysregulation of this component of the CDK9 pathway is prominent in a number of hematologic malignancies." (PMID 29471852, 2018). "In this study we show that combinational treatment of cancer cells with MSCT-EVs and the CDK9 inhibitor SNS032 drastically enhanced cancer cell-killing efficacy." (PMID 28326166, 2017). "Transcription-regulating kinases CDK7, CDK9 and CDK8/19 have become actively pursued targets in cancer therapy, due in part to their effects on super-enhancers that develop during carcinogenesis and become essential for the survival of tumor cells." (PMID 28147342, 2017). "CDK7 and CDK9 are targeted by flavopiridol (DB03496), which is a cancer drug treating various types of cancer." (PMID 27801815, 2016). "Luteolin, inhibitor of cyclin-dependent kinase 9 (CDK9), can induce apoptosis in cancer cells through blocking phosphorylation of the carboxy-terminal domain of RNA polymerase II." (PMID 25815323, 2015). "Consistent with this idea, we show in the present study that simultaneous inhibition of CDK9's kinase activity and MYC's expression or function synergistically induced growth arrest and apoptosis of cancer cells." (PMID 26083714, 2015). "Aberrations in transcriptional CDKs with direct modulation of target genes have also been described in human cancer such as CDK8, CDK9/cyclin T1, CDK10, and CDK11." (PMID 25914884, 2015). "Taken all together, the data are consistent with the notion that simultaneous inhibition of CDK9's kinase activity and MYC's expression or function leads to synergistic induction of growth arrest and apoptosis of cancer cells." (PMID 26083714, 2015). "Based on the high potency of CDK9 inhibition as a cancer cell-selective TRAIL-sensitizing strategy, we envisage the development of new, highly effective cancer therapies." (PMID 24362439, 2014). "The recently identified CDK9-targeted kinases, CDK7, CDK2, and phosphatases, PP1, and PPM1A will likely emerge as novel targets for anti-HIV-1 and cancer therapeutics." (PMID 24524087, 2014). "While CDK9 is crucial for tumorigenesis and CDK9 inhibition shows efficacy in the therapy of various cancers, including LUAD 15, 16, 17, we found that CDK9 is only marginally overexpressed in LUAD and its expression was not correlated with LUAD patient survival." (PMID 40860160, 2025). "The protein network of unique cancer cell genes in the “cancer cells_vs_all-PDAC” group exhibited top 10 hub genes, including H4C6 (HIST1H4A or HIST1H4C), MYC, H3C12 (HIST1H3A or HIST1H3D), DDX21, USP7, RFC4, APEX1, CDK9, H2BC9 (HIST1H2BH), and NOP2." (PMID 40906153, 2025). "CDK9 directly regulates MYC gene expression, particularly in cancer contexts." (PMID 40163908, 2025). "Furthermore, the MYC, DDX21, USP7, RFC4, APEX1, CDK9, and NOP2 of the “cancer cells_vs_all-PDAC” group play a critical role in the metabolic reprogramming of the PDAC, contributing to the poor prognosis of PDAC." (PMID 40906153, 2025). "CDK9 inhibitors such as KB-0742 have recently entered clinical trials (e.g., Phase I/II trial NCT04718675), with preliminary pharmacodynamic data showing effective reduction of MYC expression in preclinical cancer models." (PMID 40365020, 2025). "Although CDK9 and CYP3A4 perform distinct biological functions, targeting both could yield synergistic effects in cancer treatment." (PMID 39498375, 2024). "A limitation of this study is that anti-cancer effects unrelated to CDK9 inhibition cannot be ruled out." (PMID 39117800, 2024). "Therefore, CDK9 inhibition in combination with HSP90 inhibition will prevent protective HSF1-mediated HSR and cell survival in cancer cells." (PMID 38326887, 2024).
cancer (continued). "Moreover, we showed that CDK9 inhibition activates an interferon (IFN) response, endogenous retroviruses, and immunosensitizes cancer cells to the checkpoint inhibitor anti-PD1, in vivo." (PMID 38172923, 2024). "CDK9 was expressed in almost all prostate epithelial cells, localized to the nucleus, and was more abundant in cancer compared to non-malignant samples." (PMID 39117800, 2024). "Co‐targeting of CDK9 and KRAS/MAPK signaling pathways eliminates ERK‐MYC activation and prevents feedback activation mediated by receptor tyrosine kinases, leading to more effective control of KRAS‐mutant cancers and overcoming KRASi resistance." (PMID 39254172, 2024). "This compound also inhibits the cell migration in MDA-MB-231 cancer cell lines and was reported as the first non-metal–organic structure that works as a selective CDK9/Cyclin T1 with in vivo anticancer activities." (PMID 39404419, 2024). "Moreover, our findings warrant further development of CDDD11-8, a novel oral selective CDK9 inhibitor, for clinical evaluation in TNBC and potentially for other aggressive, highly proliferative cancers addicted to transcription." (PMID 38001268, 2024). "In addition, Atuveciclib, a selective PTEFb/CDK9 inhibitor, and CT7001, a selective CDK7 inhibitor, are emerging as potential cancer treatment options, as they have entered clinical trials." (PMID 37842645, 2023). "Because cancer alterations of CDK9 do not affect its expression or kinase activity in a majority of cases, many distinct mechanisms likely account for the reliance on P-TEFb." (PMID 37811895, 2023). "Further optimization of this novel scaffold was conducted by our team with the identification of 2-phenylimidazopyrazin-3-amine 2 as a CDK9 inhibitor with submicromolar IC50 values and a potent antiproliferative effect against a panel of cancer cell lines with single-digit IC50." (PMID 37513929, 2023). "In addition, studies have shown that the inhibitors of CDK7(THZ1) or CDK9(CYC065) can disrupt abnormal MYCN-driven transcription and inhibit MYCN gene transcription, becoming potential anti-cancer drugs." (PMID 36770809, 2023). "It is fascinating how depleting the activity of the seemingly essential transcriptional kinase, CDK9, is tolerated by the normal cells but not the cancer cells." (PMID 35164752, 2022). "The role of the CDK9 in cancer pathogenesis is not fully established yet, but several studies proved it to be a poor prognostic factor in various cancers." (PMID 35092513, 2022). "There is a growing body of evidence suggesting that other cyclin-dependent kinases including CDK7, CDK8, CDK9, and CDK12 may also be important for modulating the sensitivity of cancer cells to the effects of ionizing radiation." (PMID 34932500, 2022). "We show here that recombinant TRAIL and CDK9 inhibition cooperate in killing cells derived from a broad range of cancers, importantly without inducing detectable adverse events." (PMID 34535764, 2022). "Relatively high CDK9 expression in the non-muscle-invasive and low-grade cancer groups seems to be in line with those reports." (PMID 35326643, 2022). "Given that the P-TEFb-dependent transition into productive elongation is an abundantly exploited step in regulating cellular gene expression, it is not surprising that CDK9 contributes to the progression and the maintenance of many cancer types." (PMID 34146121, 2021). "Acetyl-bufalin is a novel blocker of the CDK9/STAT3 pathway thus may have potential in therapy of NSCLC and other cancers." (PMID 33122847, 2021). "CDK9 and CDK12/13 inhibitors are currently tested for their efficiency to kill cancer cells." (PMID 34663829, 2021). "Thus, CDK9 and BRD4 have emerged as druggable targets for the development of cancer therapies, through suppression of constitutive expression of anti-apoptotic proteins." (PMID 34146121, 2021).